NR2E3 (nuclear receptor subfamily 2 group E member 3)
Description:
Orphan nuclear receptor of retinal photoreceptor cells. Transcriptional factor that is an activator of rod development and repressor of cone development. Binds the promoter region of a number of rod- and cone-specific genes, including rhodopsin, M- and S-opsin and rod-specific phosphodiesterase beta subunit. Enhances rhodopsin expression. Represses M- and S-cone opsin expression.
Synonyms: PNR; RNR; rd7; RP37; ESCS; ESCS1
Tractability: Small molecule: it belongs to a druggable protein family. PROTAC: UniProt records ubiquitination sites on it; a small molecule that binds it is known.
Target class: Nuclear hormone receptor subfamily 2; Nuclear hormone receptor subfamily 2 group E; Nuclear hormone receptor subfamily 2 group E member 3; Nuclear receptor; Transcription factor
Gene: Protein-coding gene on chromosome 15 (71,792,638 to 71,818,259, forward strand). Ensembl gene ENSG00000278570.
Subcellular location: Nucleus
Pathways (Reactome):
Gene expression (Transcription): Nuclear Receptor transcription pathway
Gene Ontology:
Molecular function: DNA-binding transcription activator activity, RNA polymerase II-specific; protein binding; RNA polymerase II cis-regulatory region sequence-specific DNA binding; sequence-specific DNA binding; nuclear receptor activity; DNA binding; DNA-binding transcription factor activity; nuclear steroid receptor activity; zinc ion binding
Biological process: positive regulation of transcription by RNA polymerase II; neuron differentiation; phototransduction; signal transduction; visual perception; intracellular receptor signaling pathway; nuclear receptor-mediated steroid hormone signaling pathway; regulation of DNA-templated transcription
Cellular component: nucleoplasm; nucleus; transcription regulator complex
Genetic constraint (gnomAD): Loss-of-function variants: 38 observed, 33.88 expected, observed/expected ratio (o/e) 1.12, 90% interval 0.87 to 1.47. The upper end of that interval is the gene's LOEUF score, 1.47, which puts it in group 6 of 6, group 1 being the genes least tolerant of losing a copy. Missense variants: 562 observed, 507.89 expected, observed/expected ratio (o/e) 1.11, 90% interval 1.03 to 1.19. Synonymous variants: 235 observed, 205.15 expected, observed/expected ratio (o/e) 1.15, 90% interval 1.03 to 1.28.
Gene-disease validity (ClinGen):
ClinGen rates the evidence that NR2E3 causes each of these diseases.
enhanced S-cone syndrome (autosomal recessive): Definitive. An autosomal recessive retinopathy in which patients have increased sensitivity to blue light; perception of blue light is mediated by what is normally the least populous cone photoreceptor subtype, the S (short wavelength, blue) cones.
inherited retinal dystrophy (autosomal dominant): Definitive. An instance of retinal degeneration that is caused by an inherited modification of the individual's genome.
Homologues: Orthologues: chimpanzee NR2E3 (98% identical), macaque NR2E3 (98% identical), pig NR2E3 (90% identical), mouse Nr2e3 (87% identical), rat Nr2e3 (87% identical), guinea pig NR2E3 (80% identical), dog NR2E3 (68% identical), tropical clawed frog nr2e3 (66% identical), zebrafish nr2e3 (64% identical), Drosophila melanogaster Hr51 (53% identical), Caenorhabditis elegans fax-1 (33% identical), Caenorhabditis elegans nhr-111 (22% identical). Paralogues in human: NR2E1 (41% identical), NR2F1 (38% identical), NR2F2 (38% identical), NR2F6 (37% identical), RXRA (33% identical), RXRB (33% identical), RXRG (32% identical), NR2C1 (31% identical), HNF4A (30% identical), NR2C2 (30% identical), HNF4G (29% identical).
Diseases named in the same sentence as NR2E3 in open-access papers:
NR2E3 is named in the same sentence as 69 diseases in open-access papers, as found by Europe PMC text mining. Sharing a sentence is not in itself a finding about the gene and the disease. The quoted sentences say what the papers report.
retinal degeneration (35 papers, 2007 to 2025). Degeneration of the retina. "NR2E3 mutations are implicated in various inherited retinal degenerations, including Enhanced S-cone syndrome." (PMID 39809731, 2025). "The Rd7 mouse harbors spontaneous mutations in Nr2e3, which cause a retinal degeneration phenotype reminiscent of ESCS patients." (PMID 38652563, 2024). "The results of this study strongly support the potential of NR2E3 as a gene modifier therapy capable of treating retinal degeneration in non-NR2E3-associated RP." (PMID 38273095, 2024). "Mutations in human NR2E3 are associated with several forms of retinal degeneration that vary in phenotype and were categorized by their clinical diagnosis as they were discovered." (PMID 32123325, 2021). "The NHR 1 family d, member 1 (Nr1d1), a NHR gene, and cofactor of Nr2e3, was identified as one of the genetic modifiers that can ameliorate Nr2e3 associated retinal degeneration." (PMID 32123325, 2021). "The retinal degeneration 7 (rd7) murine model, harboring a recessive mutation in the mouse ortholog of NR2E3, has been a well-studied disease model and recently evaluated as a therapeutic model for NR2E3-associated retinal degenerations." (PMID 33513943, 2021). "The retinal degeneration 7 (rd7) murine model, Nr2e3rd7/rd7 (rd7), lacks a functional Nr2e3 gene and is a model for all Nr2e3 associated retinal degenerations." (PMID 33513943, 2021). "Taken together, NRL/NR2E3 pathway mutations alter the balance of normal photoreceptor differentiation in the developing retina, leading to a loss of rod function and retinal degeneration." (PMID 32668775, 2020). "The rd7 retinal degeneration mouse originally described in 2000 later had its mutation mapped to NR2E3." (PMID 32668775, 2020). "In the rd7 mice where retinal degeneration occurs as a result of a spontaneous mutation in the Nr2e3 gene, reactive microglia are found under abnormal foldings (retinal rosettes) that develop in the outer nuclear layer and inner segments of photoreceptors." (PMID 31481963, 2019). "Future studies will focus on exploring the applicability of using Nr1d1 gene delivery for treating Nr2e3-associated retinal degeneration at advanced stages of disease, as well as retinal disease with other genetic causes." (PMID 24498227, 2014). "In this study we demonstrate that the nuclear hormone receptor gene Nr1d1 (Rev-Erbα) rescues Nr2e3-associated retinal degeneration in the rd7 mouse, which lacks a functional Nr2e3 gene." (PMID 24498227, 2014). "Mutations in human NR2E3 are associated with several retinal degenerations including enhanced S cone syndrome and retinitis pigmentosa." (PMID 24498227, 2014). "In the present study, we show that Nr1d1 is a genetic modifier able to ameliorate Nr2e3 associated retinal degeneration and confirm that NR1D1 and NR2E3 act synergistically to regulate genes involved in retinal development and function." (PMID 24498227, 2014). "Our findings uncover NR1D1 as a potential therapeutic target for Nr2e3 associated retinal degeneration that can compensate for Nr2e3 loss by regulating key molecular pathways associated with disease." (PMID 24498227, 2014). "Here, we demonstrate that in vivo delivery of the candidate modifier gene, Nr1d1 rescues Nr2e3 associated retinal degeneration." (PMID 24498227, 2014). "We utilize the Nr2e3rd7/rd7 mouse model to study the genetic heterogeneity observed in Nr2e3 associated retinal degeneration and to identify genetic modifiers that contribute to such variation." (PMID 24498227, 2014). "Mutations in the NR2E3-encoding gene cause various retinal degenerations, including Enhanced S-cone syndrome, retinitis pigmentosa, and Goldman-Favre disease." (PMID 24069298, 2013). "By crossing rd7 mice (a model for hereditary retinal degeneration owing to Nr2e3 mutation) with mice carrying the macrophage Fas-induced apoptosis (Mafia) transgene, we generated double-mutant mice and studied the role of the resident retinal microglia." (PMID 23828046, 2013).
retinal degeneration (continued). "This functional analysis in living cells lead to further understanding of potential disease mechanisms in NR2E3-linked retinal degenerations." (PMID 19823680, 2009). "In preclinical studies, various doses of AAV5-hNR2E3 administered during the early to intermediate stages of retinal degeneration in rd7 or RhoP23H+/− mice models restored homeostasis by resetting key Nr2e3-associated pathways, and resulted in improved photoreceptor survival and function." (PMID 41234928, 2025). "Interestingly, dysplastic changes occur in human retinal degenerations with mutated NR2E3, indicating a previously unrecognized proliferative response." (PMID 39809731, 2025). "Additionally, the observation of the dysplastic appearance and proliferative response observed in human retinal degenerations associated with mutated NR2E3 opens up intriguing avenues for further research." (PMID 39809731, 2025). "Mutations in the modifier gene nuclear hormone receptor NR2E3 are associated with several types of retinal degeneration including clumped pigmentary retinal degeneration (CPRD), Goldmann–Favre syndrome (GFS), enhanced S-cone syndrome (ESCS), and autosomal dominant retinitis pigmentosa (adRP)." (PMID 38273095, 2024). "The rd7 mouse is a model for Nr2e3 associated retinal degenerations." (PMID 32123325, 2021). "More recently, the rd7 model has also been used to evaluate targeted gene therapy strategies due to its novel similarity in clinical phenotype to human patients with NR2E3-associated retinal degenerations." (PMID 33513943, 2021). "Longitudinal data suggests that patients with mutations in NR2E3 may have preserved central acuity, or milder progression of disease compared to other retinal degenerations unless macular schisis or cystoid macular edema is present." (PMID 32668775, 2020). "Retinal degeneration in rd7 mice is caused by a spontaneous mutation in the Nr2e3 gene." (PMID 23828046, 2013). "Phenotypic variations in the retina include disease onset and severity, such as that observed for the retinal degeneration 7 (rd7) mouse model, which harbors a mutation in the nuclear hormone receptor Nr2e3 and models the human retinal disease enchanced S-cone syndrome." (PMID 21779340, 2011). "Furthermore, a previous study showed that NR2E3 gene therapy applied to the RhoP23H−/− mouse model could rescue retinal degeneration associated with RP." (PMID 39451224, 2024). "Thus, Nr1d1 is a strong candidate to modify the effects of Nr2e3-associated retinal degeneration." (PMID 24498227, 2014). "In both NRL and NR2E3 mutant mouse models, failure to fully specify rod-photoreceptors leads to retinal degeneration." (PMID 40758714, 2025). "More than two decades of research in multiple mouse models of RP with different underlying mutations (rd1, Rho−/−, RhoP23H, rd16, and rd7) has established that NR2E3 can rescue retinal degeneration and RP disease progression." (PMID 41234928, 2025). "Here we expand the studies to evaluate the efficacy and longitudinal impact of the NR2E3 therapeutic by examining three different doses administered at early or intermediate stages of retinal degeneration in the rd7 mice." (PMID 39019967, 2024). "Nuclear hormone receptor NR2E3 can modulate gene expression levels associated with RP through epigenetic regulation, and the molecular reset mediated by NR2E3 was shown to reduce retinal degeneration in RP mouse models." (PMID 38474086, 2024). "Based on this principle, an intriguing approach has been proposed — treating retinal degeneration by converting rods into cones through the inhibition of Nrl or Nr2e3 in adult retina." (PMID 39499900, 2024). "Our previous publication revealed the novel finding that the modifier gene Nr2e3 can treat retinal degeneration in several mouse models of RP." (PMID 38273095, 2024). "This study demonstrates the effectiveness of different doses of NR2E3 at reducing retinal degeneration and informs dose selection for clinical trials of RhoP23H-associated RP." (PMID 38273095, 2024).
retinal degeneration (continued). "This was a pharmacological study to demonstrate the efficacy of dosage and longitudinal impact of NR2E3 modifier gene therapy to treat retinal degeneration in the RhoP23H+/− mouse when administered during early/intermediate degeneration." (PMID 38273095, 2024). "In our previous studies we demonstrated that subretinal administration of one Nr2e3 dose attenuated retinal degeneration in rd7 mice for at least 3 months." (PMID 39019967, 2024). "Like Nrl, several studies have demonstrated that disrupting Nr2e3 can preserve cone morphology and function in mouse models of retinal degeneration." (PMID 39499900, 2024). "Dysfunctional NR2E3 leads to increased S-cones and rod degeneration in humans, as well as retinal degeneration in rd7 (Retinal degeneration 7) mutant animals." (PMID 37367481, 2023). "Remarkably, Nr2e3 administered therapy resulted in reduced retinal degeneration as observed by increase in photoreceptor cells, improved electroretinogram, and a dramatic molecular reset of key transcription factors and associated gene networks." (PMID 32123325, 2021). "Immunohistochemical analysis of blue and green cone opsins and rhodopsin was performed to determine if Nr2e3 therapy can restore opsin expression and thus provide a molecular reset in retinal degeneration models." (PMID 32123325, 2021). "This study demonstrates a novel approach to gene therapy and suggests that Nr2e3 can potentially serve as a broad-spectrum gene therapy to attenuate retinal degeneration." (PMID 32123325, 2021). "The ability of Nr2e3 to rescue retinal degeneration before disease onset was tested by subretinal delivery of AAV8-Nr2e3 in five mouse models of RP." (PMID 32123325, 2021). "The potency of Nr2e3 as a therapeutic is clearly demonstrated by its ability to attenuate retinal degeneration and restore retinal integrity in several RP models at the early to intermediate stage of the disease." (PMID 32123325, 2021). "In this study, the nuclear hormone receptor gene Nr2e3 was evaluated for efficacy as broad-spectrum therapy to attenuate early to intermediate stages of retinal degeneration in five unique mouse models of retinitis pigmentosa (RP)." (PMID 32123325, 2021). "Although the authors assayed retina histology, gene expression, and ERG after only 1 week of treatment, the potential of NR2E3 inhibition to slow retinal degeneration in vivo represents an intriguing possibility for treatment of RP." (PMID 32668775, 2020). "The retinal degeneration 7 (Nr2e3rd7/rd7 here referred to as rd7 for the sake of simplicity) mutant mouse lacks NR2E3 and has been used as a model for ESCS." (PMID 23650562, 2013). "Studies of rd7 mouse retinas, a murine model with a homozygous insertion of a L1 retrotransposon into exon 5 of Nr2e3 gene, have also revealed a two fold increase in S-cone number, retinal dystrophy at early stages and slow retinal degeneration." (PMID 17438525, 2007). "In line with the OCT results, histologic analyses by H&E staining and immunofluorescent staining showed that the ONL of the treated retina became significantly thicker than the untreated retina, further indicating the rescue of retinal degeneration following Nr2e3 knockout." (PMID 38408137, 2024). "AAV-delivered CRISPR-cas9 Nr2e3 gene knockdown in Rd10 mice prevents retinal degeneration." (PMID 36840007, 2023). "Studies have confirmed that NR1D1 reverses the functional NR2E3 gene in retinal degeneration mice." (PMID 37740201, 2023). "Fundus and histology show the attenuation of retinal degeneration by Nr2e3 therapy in each model." (PMID 32123325, 2021). "Given the role of NHRs such as NR2E3, to modulate numerous key biological networks essential for maintaining retinal homeostasis, this study evaluated Nr2e3 as a broad-spectrum genetic modifier with the potential to attenuate retinal degeneration in several different mouse models." (PMID 32123325, 2021).
retinal degeneration (continued). "Under the control of the NRL promoter, NR2E3 expression in rd7 NR2E3-/- mice prevented retinal degeneration, supporting the hypothesis of NR2E3 favoring rod homeostasis." (PMID 32668775, 2020). "Interestingly, a report using a gene therapy NR2E3 overexpression strategy also showed promise in mouse retinal degeneration models." (PMID 32668775, 2020). "This suggests that modulation of the NR2E3 pathway (either inhibition or upregulation) in mouse models of RP may therefore slow retinal degeneration by either similar or distinct mechanisms." (PMID 32668775, 2020). "NR2E3-null mutations cause retinal degeneration and lack of color vision in mice, whereas various point mutations have been associated with enhanced S-cone syndrome (ESCS)." (PMID 24069298, 2013). "Consistent with the human phenotypes, a loss of function mutation in Nr2e3, caused by a L1 insertion, leads to increased S-cone function, slow degeneration of photoreceptors, and abnormal lamination of the outer nuclear layer with rosette formation in the retinal degeneration 7 (rd7) mouse." (PMID 19898638, 2009). "Importantly, deleterious phenotypes such as retinal degeneration seen in human patients with germline mutations of NRL or NR2E3 have not been observed in long-term deletion of NRL in mature retina in mouse models." (PMID 32668775, 2020). "In addition, Rev-Erbα can rescue Nr2e3-mediated retinal degeneration in mice." (PMID 31409842, 2019). "Potential interacting molecules involved in retinal degeneration or visual cycle, including MINDY3, EPG5, miR‐548b‐3p, OTX2, miR‐519d, LRAT, and NR2E3, were selected based on the STRING and miRDB (MicroRNA Target Prediction Database) databases." (PMID 40956390, 2025). "Deletion of a 380-nt fragment in the mouse Nr2e3 coding region disrupts the DNA-binding domain (DBD), leading to similar retinal degenerations observed in the rd7 mouse model." (PMID 39809731, 2025). "The photoreceptor-specific nuclear receptor Nr2e3 is not expressed in Nr2e3rd7/rd7 mice, a mouse model of the recessively inherited retinal degeneration enhanced S-cone sensitivity syndrome (ESCS)." (PMID 34561487, 2021). "A pragmatic therapeutic goal for RP patients would be the reprogramming of rod photoreceptors to avoid manifestations of retinal degeneration, rather than phenocopying germline NRL or NR2E3 mutations." (PMID 32668775, 2020). "The rd7 mouse, lacking Nr2e3, exhibits an increase in S cones and slow, progressive retinal degeneration." (PMID 24498227, 2014). "Interestingly, our real time PCR results revealed that RP models showed very low to no expression of Nr2e3 and other key transcription factors evaluated in this study (Nrl, Crx, Trb, Rora, and Nr1d1), which likely contributed to the progression of retinal degeneration in each model." (PMID 32123325, 2021).